MMP13 (matrix metallopeptidase 13)
Diseases named in the same sentence as MMP13 in open-access papers (continued):
Sharing a sentence is not in itself a finding about the gene and the disease.
breast tumors (continued). "Taken together, our data point to MMP-13 as a target in breast tumors with Pit-1 overexpression." (PMID 25527274, 2014). "Finally, by immunohistochemistry we correlated Pit-1 with MMP-1 and MMP-13 protein expression in 110 human breast tumors samples." (PMID 25527274, 2014). "Collagen I is the most abundant fibrillar collagen in mammals, is a substrate for MMP-13, and is typically increased in breast tumor- versus normal mammary gland-associated stroma." (PMID 24010522, 2013). "MMP-13 was co-expressed by human breast tumour bone metastases with its activator MT1-MMP." (PMID 22032644, 2011). "Next, the in vitro MMP-13 silenced breast tumour model results were checked in vivo." (PMID 22032644, 2011). "Experimental evidence suggests that matrix metalloproteinase-13 (MMP-13) protein may promote breast tumor progression." (PMID 18373849, 2008). "Thus, the differential expression of MMP-13 in breast tumor progression may be regulated by a mechanism different from those for MMP-2 and MMP-9." (PMID 18373849, 2008). "CTSG can also activate pro-MMP-9 to cut and release active transforming growth factor β (TGF-β), MMP-13, and RANKL at the tumor-bone interface of osteolytic lesions induced by breast tumors." (PMID 35935989, 2022). "Mass spectrometric data from 125 breast tumour samples showed CTHRC1, POSTN and MMP13 to all be significantly higher in breast tumour tissue relative to normal while SFRP4 and FNDC1 levels were unaffected." (PMID 36190948, 2022). "a Metastasis-free survival (MFS) curves for patients with breast tumors according to Low-ETV4 (n = 12), High-ETV4 and Low-MMP13 (n = 243), or High-ETV4 and High-MMP13 (n = 9) mRNA levels." (PMID 29996935, 2018). "The relevance of the present experimental model data was supported by the finding that MMP-13 and MT1-MMP were co-expressed in human metastatic breast tumour foci in the bone." (PMID 22032644, 2011). "In mice without MMP13 KO, longer and thicker collagen I fibres are more frequently oriented parallel to the breast tumour–host boundary." (PMID 40243781, 2025). "Finally, in human breast tumors there is a significant correlation between Pit-1 and MMP-1 and MMP-13 expression in both tumor and fibroblast cells, suggesting a relationship between Pit-1 and MMPs expression in Pit-1-induced metastasis to lung." (PMID 25527274, 2014). "Human collagenase-3 (MMP-13), a new member of the MMP family, is expressed by breast tumors." (PMID 18554405, 2008). "Thus, it is tempting to speculate that high Pit-1 levels in fibroblasts from breast tumors could induce increased MMP-1 and MMP-13 expression, which in turn may increase collagen degradation and facilitate the dissemination of tumor cells to lung." (PMID 25527274, 2014). "Thus, MMP-13 may be independent of MMP-2 and MMP-9 as a marker as well as a regulator of breast tumor progression." (PMID 18373849, 2008).
disc degeneration (18 papers, 2007 to 2025). "The results of these studies suggest that Panax notoginseng might be useful for inhibiting the production of TNF-α, MMP-13, IL-1β and NO, which are associated with disc degeneration, and these effects could have caused the positive changes in disc height observed in this study." (PMID 23419188, 2013). "In this study, we first demonstrated that RCAN1.4 is positively associated with disc degeneration and that hypoxia-induced downregulation of RCAN1.4 activated the calcineurin/NFAT signaling pathway to facilitate SOX9 and MMP13 expression." (PMID 32467610, 2020). "Three, recent studies suggest that expression of MMP-3, MMP-9, and MMP-13 is increased in degenerative disc disease." (PMID 30704538, 2019). "Immunohistochemistry staining demonstrated that the levels of TNF-α, IL-1β and MMP-13 were increased in the pathogenesis of intervertebral disc disease." (PMID 28498809, 2017). "A single impact applied to the lumbar disc without causing structural damage to the lumbar spine also triggered significant upregulation of Piezo1, NLRP3 inflammatory vesicles, catabolic (MMP-9, MMP-13) and pro-inflammatory gene (IL-1β) expression and induced disc degeneration (IDD)." (PMID 35154133, 2022). "For example, one study demonstrated that leptin promotes catabolic activity in rat NPCs by upregulating the expression of MMP‐1, MMP‐13, ADAMTS4, and ADAMTS5 via activation of the JAK2/STAT3 pathway, suggesting a mechanism contributing to disc degeneration." (PMID 41497807, 2025). "Analyses also showed that Shinbaro 2 administration led to a dose-dependent reduction in disc-degeneration-related factors, such as matrix metalloproteinase (MMP) 9, MMP13, and ADAMTS-5, at the protein and mRNA levels." (PMID 39201178, 2024). "MMP-13 and ADAMTS-5 have been reported to be involved in the degradation of disc matrix, exacerbating disc degeneration." (PMID 33936382, 2021). "Third, we studied the role of EA played in the ECM regulatory factors, including MMP-13, TIMP-1, and BMP-2, in disc degeneration." (PMID 24987434, 2014). "Here, we demonstrate for the first time that, in cells extracted from human NP tissue, increased levels of p16INK4a were associated with increased gene expression of the degradative enzymes MMP-13 and ADAMTS 5, which is characteristic of disc degeneration." (PMID 17498290, 2007). "The p38 MAPK can affect the expression of MMP1, MMP3, MMP13, IL-6, IL-8, COX-2, iNOS, and TGF-β, as well as control the expression of anabolic and anti-catabolic genes such as proteoglycans, collagen I protein and collagen II, leading to disc degeneration." (PMID 38313000, 2023). "In addition, we performed immunofluorescence staining for matrix metalloproteinase enzyme (MMP-13), a key enzyme involved in the degradation of collagenous ECM in cartilage tissue during disc degeneration." (PMID 36991502, 2023). "Our findings revealed that digoxin treatment inhibited the upregulation of MMP-13 and ADAMTS4/5 induced by TNF-α, leading to restoration of the expression of Col-2 and Aggrecan, indicating its potential role in inhibiting ECM degradation in disc degeneration." (PMID 37790932, 2023). "In some experiments on mice that have led to disc degeneration, abnormal expression of type X collagen, increased apoptosis, inappropriate intervertebral disc ossification, and elevated expression of COL10A1, Runx2, MMP-13, etc. were observed in degenerative NP." (PMID 34307661, 2021).
diabetes (17 papers, 2012 to 2025). "Nonetheless, to our knowledge, our finding is the first report to demonstrate involvement of MMP-13 in genetic diabetic kidney remodeling, since Akita is a genetic diabetic mouse due to spontaneous point mutation in the Ins2 gene." (PMID 28883608, 2017). "For example, high expression of Pla2g5 and/or Prl5a1, as well as low expression of Ankrd2 and/or Pappa2, indicates exposure to diabetes, while low expression of Kcnk2 and/or Mmp13 indicates exposure to breeder diet." (PMID 22701643, 2012). "Therefore, we investigated the effect of Nimbidiol on the expression of MMP-9 and MMP-13 in the diabetic kidney." (PMID 36522378, 2022). "In addition, it was found that BRD4 inhibited the expression of MMP-13 in diabetics-related degeneration of intervertebral disc via modulating autophagy, NF-κB, and MAPK pathways." (PMID 33849578, 2021). "Therefore, MMP-2, MMP-9, MMP-11, MMP-13, and TIMP-4 could be important biomarkers to evaluate in diabetes and associated disorders." (PMID 33419373, 2020). "Thus, in addition to angiogenic factors, MMP-9 and MMP-13 may play a role in wound healing in patients with diabetes." (PMID 25884474, 2015). "Diabetes leads to severe synovial inflammation and elevated TNF-α levels in obese KOA patients, upregulating pro-inflammatory factors and MMP-13, and damaging joints." (PMID 41158135, 2025). "Of note, compared to WT, diabetic kidney showed a significant increase in the expression of MMP-9 and MMP-13 at mRNA (2.18 and 0.98 fold, respectively) and protein (0.54 and 0.46 fold, respectively) levels." (PMID 36522378, 2022). "Treatment with GYY substantially mitigated the elevated expression of RXRα, RXRβ and RARγ1, suggesting an RXR and RAR regulatory role by GYY to mitigate PAI-1, MMP-9, MMP-13; thus, ECM turnover in diabetic kidney." (PMID 34680110, 2021). "In diabetic mice (DM), myocardial fibrosis is clearly related to the expression of MMP7, MMP11, MMP13, and MMP16 in myocardial tissue." (PMID 33014530, 2020). "High levels of glucose in diabetes upregulates the expression of MMP9 and MMP13 in tendon cells 38 and the elevated MMP9 levels can further lead to cardiac fibrosis and myocyte uncoupling." (PMID 25824442, 2015). "It has been postulated that diabetes negatively impacts the tendon ECM profile not only due to AGE formation but also as a result of increased MMP-9 and MMP-13 expression in tendon cells." (PMID 23981230, 2013). "In diabetes, serum MMP13 was not different in ulcerated diabetic patients compared to healthy control individuals, but a focal increase in MMP-13 expression was observed in atherosclerosis." (PMID 38576768, 2024). "Secondly, there are no strict restrictions on the types of gastritis control cases, and some diseases that may affect serum EFNA1 and MMP13 levels, such as infection, ischemia, and diabetes, are also not considered." (PMID 38987376, 2024).
lymph node metastasis (16 papers, 2008 to 2023). "The increased expression of either leptin receptors (ObRs) or MMP-13 was significantly associated with lymph node metastasis and tended to be associated with the TNM stage in patients with pancreatic cancer." (PMID 37444627, 2023). "It has been reported that the overexpression of MMP-13 was associated with invasive capacities of the malignant cells, including lymph node metastases, and shorter overall survival in several types of malignancies." (PMID 34452576, 2021). "It is believed that the overexpression of hypoxia-induced MMP-13 in NPC-derived EVs can induce changes in tumor microenvironment whereas MMP-13 levels are strongly associated with lymph node metastasis, clinical stage and poor prognosis in NPC patients." (PMID 30322133, 2018). "Consistently, we also found the association of MMP-13 expression with lymph node metastasis and the pathological stage." (PMID 25948792, 2015). "The increased expression of either Ob-Rb or MMP-13 was significantly associated with lymph node metastasis and tended to be associated with the TNM stage in patients with pancreatic cancer." (PMID 25948792, 2015). "In the current study, overexpression of MMP13 protein showed significant association with advanced staging and lymph node metastasis." (PMID 25401159, 2014). "Moreover, high MMP-13 expression was significantly associated with T classification (P = 0.043), lymph node metastasis (P = 0.008) and clinical stage (P < 0.01) of patients with NPC." (PMID 29515112, 2018). "It was recently shown that leptin, which uses ROCK as a critical signal mediator, induces migration and invasion of human pancreatic cells via MMP13 up‐regulation, while increased MMP13 expression in patients was associated with lymph node metastasis and pathological stage." (PMID 28031255, 2017). "Highly expressed MMP13 protein also showed a significant correlation with tumor staging and lymph node metastasis." (PMID 35909962, 2022). "We discovered that serum MMP-13 is a valuable biomarker in prediction of cSCC lymph node metastasis." (PMID 34266392, 2021). "High level of MMP13 protein expression showed a significant correlation with lymph node metastasis (P = 0.011) and tumor staging (P = 0.002)." (PMID 25401159, 2014). "In contrast, high expression of MMP13 protein was significantly correlated with lymph node metastasis (P = 0.011), tumor staging (0.002), and a trend towards association with tumor sizes (T3 and T4, P = 0.063)." (PMID 25401159, 2014). "Furthermore, MMP-13 levels were closely associated with HIF-1α expression (r = 0.679, P < 0.001), lymph node metastasis, clinical stage (all P < 0.05) and poor prognosis in NPC patients (P < 0.01)." (PMID 29515112, 2018). "Serum MMP-13 levels show high sensitivity and specificity for the differentiation of invasive cSCC and cSCC in situ, and the prediction of lymph node metastasis, suggesting serum MMP-13 might serve as a valuable biomarker for early detection of cSCC invasiveness and monitoring of cSCC progression." (PMID 34266392, 2021). "After surgery, the MMP-13 level decreases and, when raising again, can predict an invasive SCC and lymph node metastasis; thus MMP-13 can represent a reliable biomarker for invasiveness and tumor progression monitoring." (PMID 35572966, 2022). "Univariate analyses showed that T classification (P = 0.034), lymph node metastases (P < 0.01), clinical stage (P < 0.01), HIF-1α expression (P < 0.01) and MMP-13 expression (P < 0.01) were all significantly correlated with patients’ survival." (PMID 29515112, 2018). "Within this group of proteases, only MMP9, MMP13, MMP14, and TIMP1 have correlated with depth of tumoral invasion, lymph node metastasis, and an unfavorable prognosis in GC patients." (PMID 24669030, 2014). "High levels of MMP-13 in these two tissue compartments were strongly correlated with each other, and further correlated with Her-2/neu, TIMP-1, lymph node metastasis and decreased overall survival." (PMID 18373849, 2008).
lymph node metastasis (continued). "Significantly higher levels of serum MMP-13 were also detected in subjects with lymph node metastasis compared with those without lymph node metastasis." (PMID 34266392, 2021). "Recent studies showed that the nonmucinous ACs had a higher tumor derived MMP13 protein levels than MACs and SCs, which are more invasive and have a higher frequency of lymph node metastasis than nonmucinous ACs." (PMID 25880591, 2015). "In addition, increased expression of MMP13 protein in ODLs and OSCC as compared to normal oral mucosa and its correlation with advanced stage and lymph node metastasis of OSCC provide further evidence for its role in genesis and progression of OSCC." (PMID 25401159, 2014).
atherosclerosis (15 papers, 2013 to 2024). A disease characterized by the build-up of fatty material and calcium deposition in the arterial wall resulting in partial or complete occlusion of the arterial lumen. "Other atherosclerosis risk factors, such as Mmp13, M-CSF, sdf-1α, and Integrinβ2, are also targets of miR-130a-3p possibly; however, only Mmp13 and ICAM-1 were upregulated in accordance with downregulated miR-130a-3p." (PMID 32855961, 2020). "Endogenous FOXO3a is activated in human atherosclerosis, and in culture induces MMP13 induction and secretion, ECM breakdown, and VSMC apoptosis." (PMID 29326312, 2018). "FOXO3a activation promotes atherosclerosis and medial degeneration and increases neointima after injury that is partly dependent on MMP13." (PMID 29326312, 2018). "FOXO3a activation in SM22αFOXO3aA3ER mice induces VSMC apoptosis, increases MMP13 expression and activity, promotes atherosclerosis, increases necrotic core and reduces relative fibrous cap areas, and promotes medial degeneration." (PMID 29326312, 2018). "The FOXO3a-MMP13 axis directly links vascular smooth muscle cell apoptosis and matrix breakdown in atherosclerosis and vascular remodeling." (PMID 29326312, 2018). "We found increased levels of MMP-9 and MMP-13 in human endarterectomies with advanced atherosclerosis, together with significant amounts of extracellular matrix (ECM) metalloproteinase inducer EMMPRIN." (PMID 30347750, 2018). "FOXO3a activation promotes atherosclerosis and medial degeneration, together with increased necrotic cores and reduced relative fibrous cap areas, and FOXO3a and MMP13 regulate arterial remodeling." (PMID 29326312, 2018). "Instead, we observed decreased expression of MMP13, which is the main collagenase of mouse atherosclerosis." (PMID 26197235, 2015). "Previous study has verified that elevated SASP mRNA expression (including Il-1α, Tnf-α, Ccl2, Mmp12, and Mmp13) significantly increases in senescent foamy macrophages during atherosclerosis, which has the similar characteristics of SASP in senescent macrophages during lung fibrosis." (PMID 34023858, 2021). "MMP-13 has received attention because of its central role in the cartilage degradation network and it is also proposed to have anti-fibrotic activities in murine models of atherosclerosis." (PMID 32098116, 2020). "In this study, our data support a novel effect of curcumin on the expression level of EMMPRIN, MMP-9 and MMP-13, suggesting that curcumin could be a potential therapeutic agent for ameliorating the development of atherosclerosis plaque." (PMID 25241044, 2014). "Previous reports demonstrated that MMP-1 and MMP-13 might be overexpressed in both human and experimental atherosclerosis." (PMID 23365489, 2013). "MMP-13 might be overexpressed in both human and experimental atherosclerosis as well." (PMID 25241044, 2014). "The levels of MMP-9, MMP-13, and EMMPRIN were determined by immunohistochemistry in human crossed sections of carotid endarterectomy specimens, showing extensive atherosclerosis, as shown by hematoxylin/eosin, and Masson Trichrome staining." (PMID 30347750, 2018). "Although some studies have suggested the anti-atherosclerosis activity of curcumin, the mechanism by which curcumin regulates MMP-9, MMP-13 and EMMPRIN is currently unknown." (PMID 25241044, 2014). "Because MMP-9 and MMP-13 plays an important role in the rupture of atheromatous plaques, our findings shed novel insight into the regulatory mechanism of MMP-9 and MMP-13 expression, the function of AMPK, and a potential treatment of atherosclerosis by curcumin." (PMID 25241044, 2014).
bladder cancer (15 papers, 2012 to 2025). "On the other hand, recent studies of SENP2 in bladder cancer showed that the expression of SENP2 is downregulated in bladder cancer cells, causing an increase of MMP13 for cell migration and invasion." (PMID 29955155, 2018). "SENP2 appeared to inhibit bladder cancer cells migration and invasion in vitro, through suppressing MMP13 in BC cells." (PMID 26369384, 2015). "SENP2 appeared to inhibit migration and invasion of bladder cancer cells in vitro, through suppressing MMP13 in BC cells." (PMID 26369384, 2015). "CCL17-CCR4 axis can promote bladder cancer metastasis via activating ERK/MMP13 pathway." (PMID 39473097, 2025). "The binding of chemokine CCL17 to its receptor CCR4 was shown to enhance MMP-13 expression in bladder cancer through the activation of extracellular signal-regulated kinase (ERK) 1/2 signalling, and in colorectal cancer through the activation of ERK/NF-κB signalling." (PMID 35805035, 2022). "However, SENP2 functions as a tumor suppressor in bladder cancer by limiting the expression of MMP13 and inhibiting the invasion and migration of bladder cancer." (PMID 33273928, 2020). "Small ubiquitin related modifier (SUMO)-specific protease 2 (SENP2) altered SUMOylation of the MMP-13 promoter and enhanced MMP-13 expression in bladder cancer." (PMID 35805035, 2022). "The roles of MMP-10, MMP-11, MMP-13, and MMP-15 in bladder cancer have not been widely studied, but MMP-13 revealed higher expression in tumors with a higher stage and grade." (PMID 22852097, 2012). "Our analysis confirmed the novel function of UCA1 in bladder cancer and provided another potential mechanism that UCA1 may compete with miR-143 to regulate the expression of MMP13 and PTGS2, both of the coding genes were identified here as dysregulated but lack fully elucidation in bladder cancer." (PMID 27863388, 2016). "In addition, MMP9, MMP13, and TIMP1 are expressed in many bladder cancers and may mediate tumor invasiveness through extracellular matrix regulation." (PMID 23209855, 2012).